CDK4 (cyclin dependent kinase 4)
Diseases named in the same sentence as CDK4 in open-access papers (continued):
Sharing a sentence is not in itself a finding about the gene and the disease.
breast cancer (continued). "Treatment for hormone receptor-positive (HR+) advanced breast cancer includes aromatase inhibitors and CDK4/6 inhibitors such as palbociclib." (PMID 41754917, 2026). "CDK4/6 inhibitors (CDK4/6i) improve outcomes for estrogen receptor (ER) positive/HER2-negative breast cancers (BCs), yet intrinsic and acquired resistance exist." (PMID 41593097, 2026). "CONCLUSIONS: Ki67 appears to be a prognostic factor in advanced breast cancer patients treated with CDK4/6i." (PMID 41688937, 2026). "Simultaneously, it downregulates cyclins and CDKs, including cyclin D1 and CDK4/6, which are frequently overexpressed in breast cancer and are essential drivers of G1 to S phase transition." (PMID 41496977, 2026). "METHODS: We conducted a retrospective analysis of patients with advanced breast cancer receiving CDK4/6i at our cancer center between 2018 and 2023." (PMID 41688937, 2026). "In luminal ER+ breast cancer, CDK4/6 activity is a major driver of malignancy and is closely linked to ER signaling." (PMID 41596432, 2026). "In this study, we re-evaluated abemaciclib, a clinically approved CDK4/6 inhibitor for breast cancer and uncovered its previously unrecognized therapeutic potential in AD via CDK4/6-independent mechanisms." (PMID 41532696, 2026). "BACKGROUND: Cyclin-dependent kinase 4/6 inhibitors (CDK4/6i) are the standard of care in advanced breast cancer." (PMID 41688937, 2026). "One of the key ER target genes is CCND1, encoding Cyclin D1, which is consistently overexpressed in ER+ breast cancers and plays a central role in maintaining sustained CDK4/6 activation." (PMID 41596432, 2026). "Cyclin-dependent kinase 4/6 inhibitors (CDK4/6i) have transformed the treatment landscape for estrogen receptor-positive (ER+) breast cancer, yet resistance remains a major clinical challenge." (PMID 41594633, 2026). "Validating the genome-wide analyses, we found that resistance of breast cancer cells to the CDK4/6 inhibitor palbociclib conferred by TGFβ stimulation was functionally dependent on SOX4." (PMID 41639049, 2026). "Dysregulation of the PI3K/AKT/mTOR pathway is among the most frequent molecular alterations in breast cancer and plays a central role in resistance to both endocrine therapy and CDK4/6 inhibition." (PMID 41510186, 2026). "Outcomes for patients with hormone receptor-positive, HER2-negative (HR+HER2-) advanced breast cancer have improved considerably in recent years and CDK4/6 inhibitors are the preferred first-line therapy for most patients." (PMID 42266036, 2026). "This review aims to provide current evidence on CDK4/6 inhibitors in HR+/HER2- breast cancer, highlighting their mechanisms, interaction with endocrine resistance, combination strategies, and emerging biomarkers guiding personalized therapy." (PMID 41930171, 2026). "Combined use of circESR1 ASO and CDK4/6 inhibitors were shown to be an effective therapeutic approach overcoming antiestrogen resistance in breast cancer xenograft models." (PMID 41608617, 2026). "Combination of CDK4/6i with endocrine therapy has significantly improved PFS in patients with hormone receptor (+)/HER2(−) advanced breast cancer by effectively targeting dysregulated cell cycle progression." (PMID 41510186, 2026). "ER-positive ZR75.1 breast cancer cells transduced with retroviral vectors were treated with endocrine (tamoxifen, fulvestrant) or CDK4/6i monotherapies (abemaciclib, palbociclib, ribociclib) or a combination of fulvestrant and ribociclib." (PMID 41677624, 2026). "The optimal therapy after cyclin‐dependent kinase 4/6 inhibitor (CDK4/6i) failure in hormone receptor-positive/human epidermal growth factor receptor 2-negative (HR + /HER2 - ) advanced breast cancer (BC) remains undefined." (PMID 41862468, 2026). "In ribociclib-resistant breast cancer cells, CDK4/6 inhibitors activate the PI3K/AKT pathway and phosphorylate AKT via PDPK1." (PMID 40303296, 2025).
breast cancer (continued). "Combined inhibition of mTOR and CDK4/6 has been positively evaluated in patients with advanced breast cancer showing acceptable safety profiles." (PMID 40260297, 2025). "Recent studies showed that systemic inflammatory markers were correlated with the prognosis in breast cancer patients treated with CDK4/6 inhibitors." (PMID 40697377, 2025). "Recent studies unveiled that the elevation of cell cycle regulators (such as CDK7, CDK6, and CCNE1), and activation of the interferon (IFN) pathway were critical for developing CDK4/6i resistance in breast cancer." (PMID 39667501, 2025). "Our dataset includes a total of eight biopsies derived from four patients that received a CDK4/6 inhibitor in combination with endocrine therapy, which is a common combination therapy in metastatic HR+ breast cancer." (PMID 40404617, 2025). "Collectively, our findings support the potential of Simvastatin as a candidate for targeting CDK4 to induce G1 arrest and ultimately promote apoptosis in breast cancer cells." (PMID 40864776, 2025). "In this study, we evaluated treatment data from a group of metastatic HR-positive breast cancer patients treated with CDK4/6 inhibitors at a single center and reported factors influencing poor prognosis." (PMID 41346024, 2025). "FGFR1 amplification occurs in 15% of ER+ breast cancers, which has been shown to correlate with resistance to CDK4/6i and ET." (PMID 41357671, 2025). "The combination of CDK4/6 inhibitors (CDK4/6i) and endocrine therapy is the first-line therapy for ER+/Her2-breast cancer; however, the development of drug resistance limited the efficacy of the agents." (PMID 39667501, 2025). "ER-positivity is currently the primary biomarker guiding CDK4/6i therapy, as ER+ breast cancer cell lines demonstrate the strongest response in preclinical studies." (PMID 41226361, 2025). "Palbociclib, the first CDK4/6 inhibitor to receive FDA approval for patients with ER+/HER2− breast cancer in combination with ET, has been the most widely used CDK4/6 inhibitor." (PMID 40227585, 2025). "To identify potential tumour prognostic and predictive factors influencing the efficacy of CDK4/6i, we performed a transcriptomic analysis using the NanoString Breast Cancer 360TM (BC360TM) panel in patients with matched tumour tissue and clinical data." (PMID 40776435, 2025). "Research indicates that CDK4/6 inhibitors can stimulate autophagy in breast cancer cells by generating reactive oxygen species (ROS)." (PMID 40563591, 2025). "We have witnessed a reduction in ALND, but the recent monarchE trial confirmed the benefit of CDK4/6 inhibitors in patients with four or more metastatic lymph nodes and HR+ breast cancer, interfering with the trend in axillary surgery de-escalation." (PMID 40075646, 2025). "In conclusion, the combination of CDK4/6 inhibitors with endocrine therapy has revolutionized the treatment landscape for HR+/HER2- breast cancer patients." (PMID 40104496, 2025). "The inhibition of GPX4 has produced synergistic fatal effects when combined with CDK4/6 inhibitors and endocrine treatment in ER+ breast cancer." (PMID 40563591, 2025). "The success of CDK4/6 inhibitors in the advanced setting has encouraged their evaluation in early breast cancer." (PMID 40826108, 2025). "Our previous research indicated that highly specific agonists of ERβ inhibit the growth of ERα+ breast cancer cells in vitro, including endocrine-resistant and CDK4/6 inhibitor-resistant breast cancer cell lines." (PMID 40206590, 2025). "Targeted therapies, including CDK4/6 inhibitors and PI3K/AKT/mTOR inhibitors, such as PI3K inhibitors (e.g., alpelisib) have been approved for treating endocrine-resistant ER+ breast cancer, particularly in PIK3CA-mutated cases." (PMID 40427153, 2025). "Despite the extensive testing of several CDK inhibitors across different cancer types, only CDK4/6 inhibitors have been approved for clinical use, specifically in breast cancer patients." (PMID 39800748, 2025).
breast cancer (continued). "For instance, preclinical evidence suggests that CDK4/6 inhibitors, already approved for use in breast cancer, exhibit antitumor effects on IDHm astrocytomas harboring a CDKN2A/B deletion." (PMID 40392514, 2025). "Cyclin-dependent kinase 4/6 inhibitors (CDK4/6i) have transformed the treatment landscape for hormone receptor-positive (HR+) breast cancer." (PMID 40794455, 2025). "Several studies have established that breast cancer patients receiving chemotherapy, CDK4/6 inhibitors, and trastuzumab had attenuated immune responses after the second vaccination." (PMID 40236454, 2025). "In certain patients with HR-positive/HER2-negative breast cancer, clinical guidelines recommend endocrine therapy (aromatase inhibitor) in combination with a cyclin-dependent kinase 4/6 (CDK4/6) inhibitor as first-line treatment for advanced disease." (PMID 40346047, 2025). "We report a patient with advanced breast cancer and brain metastases who experienced long-term disease maintenance with treatment comprising CDK4/6 inhibitors and ET." (PMID 40161091, 2025). "Multiple phase III randomized trials have examined the role of CDK4/6i in early-stage HR+/HER2− breast cancer with variable results." (PMID 41228331, 2025). "This study reports a case of an Asian female with breast cancer who received a comprehensive post-operative treatment regimen, including chemotherapy, RT, endocrine therapy, and the recently approved CDK4/6i for curative adjuvant therapy." (PMID 40430137, 2025). "Additional trials are examining the safety and efficacy of combining CDK4/6 inhibitors with ICIs at various stages of breast cancer (NCT04841148 and NCT03280563)." (PMID 39930131, 2025). "Abemaciclib, ribociclib, and palbociclib are all CDK4/6 inhibitors that are currently approved in the United States and have been shown to improve the clinical outcomes for patients with breast cancer when combined with endocrine therapy." (PMID 40075623, 2025). "In two established CDK4/6i resistant breast cancer cell lines (MCF7-PalR and MCF7-AbeR), we observed downregulation of NSRP1 protein expression compared with the parental MCF7 cells." (PMID 39667501, 2025). "We analyzed 161 plasma samples from patients with metastatic ER+/HER2− breast cancer who had previously undergone treatment with endocrine therapy and CDK4/6 inhibitors." (PMID 41142848, 2025). "The fact that the essential kinase partner of cyclin D1 is CDK4 likely explains the specific sensitivity of ER+ breast cancer patients to CDK4/6 inhibitors." (PMID 40265613, 2025). "By searching for novel vulnerabilities, we identify a significantly increased lysosomal mass and altered lysosomal structure across various breast cancer cell types upon exposure to CDK4/6i in preclinical systems and clinical specimens." (PMID 39930269, 2025). "Among the key mechanisms contributing to drug resistance against CDK4/6iin HR‐positive/HER2‐negative breast cancer cells, upregulation of the PI3K/mTOR pathway is particularly common, making it a promising target for overcoming resistance." (PMID 40206206, 2025). "The aim of this study was to determine the impact of BMI on the efficacy of CDK4/6 inhibitors in patients with metastatic hormone receptor (HR)-positive breast cancer (BC)." (PMID 41346024, 2025). "Increased expression of AP-1 components, including JUN, have also been observed in models of ER+ breast cancer following CDK4/6 inhibition." (PMID 40826108, 2025). "Pharmacological inhibition of HMGB1 by CDK4/6 inhibitors has been also shown to present a powerful tool to overcome breast cancer resistance to tamoxifen by disrupting the TLR4-NF-κB pathway." (PMID 41465435, 2025).
breast cancer (continued). "Consistently, it was observed that IFNα2b treatment desensitized MCF7 cells to palbociclib with higher IC50 values, especially in the high dose group, suggesting activation of the IFN signaling confers CDK4/6i resistance in breast cancer cells." (PMID 39667501, 2025). "We retrospectively reviewed the patient with breast cancer, who was receiving adjuvant RT and CDK4/6i at Far Eastern Memorial Hospital (FEMH) in 2024 and reported the associated cancer treatment-related toxicity." (PMID 40430137, 2025). "The development of CDK4/6 inhibitors revolutionized the management of HR+/HER2− advanced breast cancer." (PMID 41502524, 2025). "Various SERD-based combination strategies are under investigation to enhance efficacy and delay progression in HR+/HER2− advanced breast cancer after CDK4/6 inhibitor and aromatase inhibitor treatment failure." (PMID 41226406, 2025). "The EMERALD trial demonstrated the efficacy of elacestrant, a novel oral SERD, in patients with ER-positive, HER2-negative advanced breast cancer who had progressed after prior endocrine therapy and CDK4/6 inhibitors." (PMID 41002573, 2025). "In MCF-7 cells, a representative luminal A breast cancer cell line with low ErbB2 expression, the G1/S transition is normally regulated by the cyclin D1/CDK4 complex via Hsp90." (PMID 41161384, 2025). "Dysregulation of the CDK4/6-Rb-E2F pathway is a common feature in various cancers, particularly in breast cancer, where CDK4/6 overactivation leads to uncontrolled cell proliferation and tumor growth." (PMID 40038413, 2025). "The cellular processes in the breast cancer cell were disrupted due to the disorganization of the CDK4/6 pathway." (PMID 40035822, 2025). "To further validate these findings using clinical data, we retrospectively analyzed microarray data from patients with luminal A subtype breast cancer who received long-term (16 weeks, n = 23) or short-term (4 weeks, n = 26) CDK4/6i therapy." (PMID 41161384, 2025). "To identify novel genes conferring insensitivity to combination endocrine therapy and CDK4/6 inhibition in ER+ breast cancer, we performed positive selection (enrichment) genome-wide knockout CRISPR/Cas9 screens in ER+ MCF-7 breast cancer cells." (PMID 40826108, 2025). "In this retrospective pharmacovigilance analysis, we identified 49,223 females with breast cancer (aged 18–100 years), in which a CDK4/6 inhibitor (palbociclib, ribociclib, or abemaciclib) was recorded as the primary suspect drug." (PMID 41496429, 2025). "Our study demonstrated that CT‐estimated low SMD at baseline robustly predicts unfavourable survival outcomes with aromatase inhibitors plus CDK4/6i in patients with luminal breast cancer." (PMID 39686815, 2025). "Cyclin-dependent kinase 4/6 (CDK4/6) inhibitors added to endocrine therapies have been shown to prolong progression-free survival in advanced breast cancer." (PMID 40888443, 2025). "The phase II BYLieve trial confirmed that adding alpelisib to ET is effective for relapsed HR+/HER2− breast cancer subjects carrying a PIK3CA mutation and progressing on CDK4/6is and ET." (PMID 40244377, 2025). "In this sense, it is also worth mentioning that a recent study demonstrated CDK7 as a putative vulnerability to overcome CDK4/6 resistance in breast cancer." (PMID 41193441, 2025). "Patients with HR+, HER2− advanced breast cancers treated with CDK4/6 inhibitors plus ET eventually experience disease progression." (PMID 40711480, 2025). "Monotherapy with immune checkpoint inhibitors remains uncommon in HR+/HER2- metastatic breast cancer, but combination therapy involving CDK4/6 inhibitors and immunotherapy is being actively investigated for patients progressing on CDK4/6 inhibitors." (PMID 40421216, 2025). "Their findings revealed that sequential treatment with CDK4/6i followed by these lysosomotropic agents was highly toxic to breast cancer cells while sparing normal cells." (PMID 39994486, 2025).
breast cancer (continued). "ER+ breast cancer patients with high FGFR1 mRNA expression at baseline show resistance to a CDK4/6 inhibitor + letrozole and had a poor prognosis in the MONALEESA-2 study." (PMID 40227585, 2025). "Combining PAK1 inhibitors with ET and CDK4/6 inhibitors represents a promising strategy to address resistance and improve patient outcomes in this aggressive breast cancer subtype." (PMID 40001545, 2025). "These approaches exemplify the paradigm of targeting resistance pathways through biomarker-guided therapy sequencing, ultimately extending the clinical utility of CDK4/6 inhibitors in advanced breast cancer." (PMID 40421216, 2025). "For patients with metastatic HR+/HER2- breast cancer, a combination of CDK4/6 inhibitors and endocrine therapy is recommended as the first-line treatment." (PMID 41487578, 2025). "In patients with HR/HER2-advanced breast cancer after progression on the CDK4/6 inhibitor, the patients who applied endocrine therapy in combination with the mTOR inhibitor had a median PFS benefit of 5.1 months." (PMID 39917165, 2025). "The PAM pathway plays a pivotal role in breast cancer progression, resistance to endocrine therapy, and resistance to CDK4/6 inhibitor therapy, making it a crucial target for breast cancer treatment." (PMID 40206206, 2025). "On the other hand, large‐scale clinical trials have demonstrated that cell cycle inhibitors, such as the FDA‐approved abemaciclib and ribociclib, which are CDK4/6 inhibitors, significantly extended progression‐free survival of breast cancer patients." (PMID 40161411, 2025). "On the other hand, real-world and retrospective studies have indicated that CDK4/6 inhibitor treatment had worse outcomes for patients with HR[+] breast cancer harboring gBRCAm." (PMID 40507226, 2025). "We demonstrate that these CDK4/6i-induced lysosomal alterations render breast cancer cells sensitive to lysosomotropic agents, such as L-leucyl-L-leucine methyl ester (LLOMe) and salinomycin." (PMID 39930269, 2025). "•CDK4/6 inhibitors use have revolutionized hormone receptor-positive/HER2-negative metastatic breast cancer treatment." (PMID 39826385, 2025). "We examined three paired endocrine therapy-resistant ER+ breast cancer cell lines in which the parental line is CDK4/6i sensitive and the evolved paired line is CDK4/6i-resistant." (PMID 40341770, 2025). "Cyclin D/CDK4/6 complexes are crucial in cancer progression, particularly in breast cancer, as revealed by study of human pathology and preclinical models." (PMID 39800748, 2025). "Over recent years, several CDK4/6 inhibitors (CDK4/6i), such as palbociclib, abemaciclib, and ribociclib, have been developed for the treatment of ER+ breast cancer, achieving significant clinical success." (PMID 41226361, 2025). "This is highly valuable as integrating molecular profiling into future studies is essential to develop personalized treatment strategies and optimize patient selection for CDK4/6 inhibitor-based therapies in HER2-positive breast cancer." (PMID 40940886, 2025). "The association of immuno-inflammatory parameters, especially RBC balanced signatures, with survival outcomes and adverse events still require investigation for advanced breast cancer (ABC) patients receiving cyclin-dependent kinase 4/6 inhibitor (CDKI)." (PMID 40502706, 2025). "In fact, the combination of PI3K inhibitors with CDK4/6 inhibitors has led to tumor regression in breast cancer cell lines, leading to the investigation of this combination in clinical trials." (PMID 40075623, 2025). "Worthy, preclinical studies on CDK4/6 inhibitors have provided promising results in malignancies other than breast cancer." (PMID 41388212, 2025). "Another exciting outcome was the PACE research, which focused on patients with advanced breast cancer who experienced disease progression after receiving CDK4/6i + AI." (PMID 41463246, 2025).